HIF1A (hypoxia inducible factor 1 subunit alpha)
Diseases named in the same sentence as HIF1A in open-access papers (continued):
Sharing a sentence is not in itself a finding about the gene and the disease.
cancer (continued). "Next, we analysed the influence of hypoxia alone, HIF1α (induced by CoCl2) or both on cancer cell viability after ascorbate exposure at increasing concentrations (0, 4, 8 and 16 mM) for 1 hr." (PMID 24330097, 2014). "This adaptive mechanism is frequently hijacked for the growth and survival of malignant cells, as evidenced by our previous finding that HIF-1α is abnormally activated in most types of cancer." (PMID 24668884, 2014). "Actually, glucose transporter 1 (GLUT1) and carbonic anhydrase IX (CAIX), which are important players in the hyper-glycolytic and acid-resistant phenotype of cancer cells, are HIF-1α targets." (PMID 25296855, 2014). "Extensive efforts have been devoted to modulate HIF-1α so that its oncogenic transcription activity can be targeted for cancer therapy." (PMID 24668884, 2014). "We defined HIF-1α as positive when more than 5 % of cancer cells showed positive nuclear expression." (PMID 23558457, 2014). "Optimal supplementation of cancer cells in tissue culture with up to 1 mM ascorbate can suppress HIF-1α induction by a range of stimuli, and can reduce indicators of cancer aggression (VEGF-A, Glut-1, and BNIP3)." (PMID 28548062, 2014). "In response to low oxygen supply, cancer cells elevate production of HIF-1α, a hypoxia-inducible transcription factor that subsequently acts to stimulate blood vessel formation and promote survival." (PMID 25140303, 2014). "Serine/threonine kinase proto-oncogene PIM2 level was induced upon hypoxia in a HIF-1α-mediated manner in cancer cells." (PMID 24505470, 2014). "In facts, C-MYC is a central modulator of cancer cell metabolism, alone or in cooperation with HIF-1α." (PMID 24980829, 2014). "As a consequence, understanding the regulation of HiF-1α dynamics is a major issue to design new anti-cancer therapies." (PMID 25338163, 2014). "Because this pathway has been found to be important for HIF-1α synthesis in various cancers, we wanted to study the effect of PTEN in combination with FIH-1 on HIF activity in GBM cell line-U87-MG." (PMID 24465898, 2014). "Dimerization of hypoxia-inducible factor-1 beta (HIF-1β) [aryl hydrocarbon receptor nuclear translocator (ARNT)] with HIF-1α is involved in various aspects of cancer biology, including proliferation and survival under hypoxic conditions." (PMID 25068796, 2014). "In order to find out the key factor contributed to the phenomenon in our experiment, HIF-1α was analysed in treated cancer cells." (PMID 25491408, 2014). "HIF-1α expression is correlated with poor prognostic clinicopathologic characteristics and survival in different cancers." (PMID 24614305, 2014). "Our data show a ROS-induced, HIF-1α-and O2-dependent cytotoxicity of ascorbate on 60 different cancer cells." (PMID 24330097, 2014). "HIF1A mRNA is highly expressed in both basal and ERBB2 subtypes compared to luminal subtypes, in agreement with the observation that HIF1A protein is expressed at higher levels in basal cancers relative to luminal cancers." (PMID 25069832, 2014). "We show that the antitumor activity and pro-apoptotic effects of DCQ are selective to cancer cells and involve the generation of ROS and suppression of HIF-1α protein expression via different mechanisms in the two cell lines." (PMID 24461075, 2014). "For example, HIF-1α-mediated lipoxygenase pathway regulates the migration and invasion of epithelial ovarian cancer cells in hypoxic condition and promotes cancer metastasis." (PMID 25937967, 2014). "HIF-1α immunohistochemistry revealed that specific cancer cell nuclei, corresponding to their Gleason score, as well as a few cell nuclei in high-grade PIN showed a positive reaction for HIF-1α." (PMID 25120646, 2014). "HIF-1α can interact with various other cancer-related transcription factors (TFs) and form a complex TF-gene transcription regulatory network during cancer development and progression." (PMID 24927122, 2014).
cancer (continued). "And SDHB was proved to be decreased due to upregulation of HIF-1α expression in CoCl2-treated cancer cells." (PMID 25491408, 2014). "Since HIF1a plays an important role in angiogenesis and promotion of cancer metastasis, MTA1 also has a part to play in both the normal wound healing and cancer." (PMID 25332145, 2014). "LXY6006 inhibited HIF-1α nuclear accumulation induced by hypoxia, and inhibited cancer cell growth as a consequence of G2/M arrest." (PMID 24925080, 2014). "Oltipraz, a cancer chemopreventive agent, has anti-angiogenic property mediated by miR-199a induction and HIF-1α inhibition." (PMID 24413338, 2014). "HIF-1 inhibition has been suggested as a therapeutic strategy in cancer and HIF-1α is actively being validated as a drug target in clinical trials." (PMID 28548062, 2014). "Here, we show that a transcriptionally active HIF-1α was up-regulated at 5% O2, both in normal and cancer cells, but only some of its target genes were elevated as a result." (PMID 24835245, 2014). "A key regulator of HIF-1α SUMOylation under hypoxia in general, including in cancer cells, is SENP1 62,63." (PMID 24634093, 2014). "The role of Hif1α in cancer is extensively studied, where upregulation of all 13 glycolytic genes to exert Warburg effect is under the influence of this transcription factor." (PMID 25333702, 2014). "Down-regulation of PTEN would result in activation of the AKT/PI3K/HIF-1α pathway, which contributed to cancer cell migration." (PMID 24912422, 2014). "Consistent with these functions, increased HIF-1α and HIF-2α protein expression has been observed in a broad array of human cancer cell types, and has been associated with poor prognosis in many cases." (PMID 25396735, 2014). "HIF-1α has been found to be overexpressed in several types of human cancer and to enhance the adaptive response of cancer to oxygen deprivation through upregulating the expression of its target genes." (PMID 25120692, 2014). "Hypoxic conditions and hypoxia-inducible factor-1α (HIF-1α)-signaling, both present in cancer metastases, confer resistance to the cancer cells toward ascorbate-induced cytotoxicity, while ascorbate inhibits HIF-1 with mechanisms of iron competition." (PMID 25202679, 2014). "In general, an elevated Hif1α activity leads to cell type specific changes in gene expression of cell lines and cancer tissues." (PMID 24952599, 2014). "To date, HIF-1α is shown to activate multiple target genes that involve in crucial aspects of cancer biology, including erythropoiesis, angiogenesis, glucose metabolism, cell proliferation/survival and apoptosis." (PMID 24927122, 2014). "Hypoxic conditions and HIF-1α-signalling, both present in cancer metastases, confer resistance to the cancer cells towards ascorbate-induced cytotoxicity, possibly via up-regulation of pro-survival HIF-1α downstream-targets (e.g. GLUT-1)." (PMID 24330097, 2014). "The hypoxia-induced factor alpha (HIF1α) is a known regulator of glucose metabolism and can mediate the Warburg effect in cancer cells." (PMID 25255370, 2014). "HIF-1α allows for survival and proliferation of cancer cells due to its angiogenic properties and its inhibition prevents the spread of cancer." (PMID 24883045, 2014). "As our data demonstrated, LCN2 expression was nearly perfectly correlated with HIF-1α levels in various cancer cells derived from solid tumors." (PMID 25467539, 2014). "Activated HIF-1α promotes the proliferation and invasion of endothelial cells, as well as migration and capillary tubule formation in malignant tumors." (PMID 24952635, 2014). "A potential cause for the cancer predisposition in VHL patients is due to misregulation of the HIFs, as both HIF1α and HIF2α have been found to correlate with poor patient prognosis." (PMID 24858415, 2014).
cancer (continued). "It has the ability to influence metabolic reprogramming, angiogenesis, metastasis and over-expression of HIF-1α has been reported in many types of cancers as well as in regional or distant metastatic lesions." (PMID 24808762, 2014). "As the activating cancer marker we chose HIF-1α, due to its tight regulation bestowing nearly complete absence in normal tissue and its ubiquitous nature in cancer cells." (PMID 25426963, 2014). "Our protein stability analyses further showed that 15-LOX-1 increased HIF-1α protein degradation in cancer cells, suggesting that 15-LOX-1 regulates HIF-1α at a posttranslational level." (PMID 24634093, 2014). "We concluded that HIF-1α can be induced at physiological oxygen tensions in normal and cancer cells, and that this basal expression is sufficient to activate the transcription of at least some of its target genes." (PMID 24835245, 2014). "Currently it is postulated that the expression of HIF-1α increases, from minimal values observed in normal endometrium to intermediate and high levels documented in the case of endometrial hyperplasia and cancer, respectively." (PMID 24745019, 2014). "HIF-1α is frequently overexpressed in common human cancers and there is a statistically significant correlation between the presence of mutant tumor suppressor gene and HIF-1α overexpression." (PMID 25548899, 2014). "In GBM, hypoxia is a characteristic feature and activation of Hypoxia Inducible Factors (HIF-1α and HIF-2α) has been associated with resistance to anti-cancer therapeutics." (PMID 24481065, 2014). "Our results highlight the importance of further investigating the functional relationship between eIFs and HIF-1α for the possible therapeutic development of anti-cancer compounds." (PMID 25166596, 2014). "We found that HBSS still can increase HIF-1α expression in A431 and A375 cancer cells as well as the primary HUVEC." (PMID 25115400, 2014). "Overexpression of the HIF-1α subunit has been observed in many human cancers and increased levels of HIF-1α protein correlate with advanced disease stages and poor prognosis." (PMID 25105148, 2014). "Lots of reports are documented on the interaction of miRNAs and HIF-1α in cancer cells and epithelial cells." (PMID 24790587, 2014). "Based on the association between HIF-1α and malignant cancer phenotypes, the inhibition of HIF-1α is becoming one of the most important strategies for cancer treatment." (PMID 25120692, 2014). "Inhibiting the molecules involved in the PI3K/Akt or HIF-1α signal transduction pathway is a possible strategy for the treatment of cancer." (PMID 24765145, 2014). "Because hypoxic responses in cancer cells are primarily mediated by hypoxia inducible factors, targeting HIF-1α directly or indirectly or eradicating intra-tumoral hypoxic regions are viable strategies to inhibit aggressive tumors." (PMID 24461075, 2014). "Similar to cancer cells, the stabilization of HIF-1α accounts for the observed metabolic changes in Aβ-resistant cells." (PMID 26316984, 2013). "The identification of hypoxia-HIF-1α-LOX pathway provides novel insights into the mechanisms that control cancer cell migration in hypoxia and reoxygenation regions." (PMID 23545606, 2013). "In hypoxic cancer cells, HIF-1α binds to the hypoxia responsive element (HRE) in the promoter region of many target genes including LOX." (PMID 23545606, 2013). "Results from our study demonstrated most high TGF-β1 cells were cancer cells expressing HIF-1α in tumors." (PMID 23723999, 2013). "It is worth noting that, in our studies, most Tregs were located in the region close to cancer cells expressing HIF-1α." (PMID 23723999, 2013). "Hyperactivity of PTEN/Akt/mTOR pathway has been proven to be pro-tumorigenic in a variety of cancers including the tumourigenesis of PCa, in which Slug was known to be a down-stream effector of hypoxia inducible factor-1α (HIF-1α)." (PMID 24130883, 2013).
cancer (continued). "That study finally isolated plasminogen activator inhibitor-1 (PAI-1) as the HIF-1α target that increases the invasive abilities of cancer cells." (PMID 24216696, 2013). "HIF-1α plays a certain role in lymphangiogenesis by closely correlating with lymphatic expression of VEGF-C in cancers, wound healing, and inflammation, and we found that deoxyshikonin upregulated the VEGF-C mRNA level during lymphangiogenesis in vitro." (PMID 23737816, 2013). "Nevertheless, digoxin was shown to block cancer growth through inhibiting HIF-1α signaling pathway in cancer cells." (PMID 23365613, 2013). "The PI3K-AKT signaling pathway has been reported to play a major role in mediating the regulation of HIF-1α expression in cancer and in response to growth factors." (PMID 23866118, 2013). "The PI3K-AKT signaling pathway plays an important role in regulating HIF-1α expression in cancer and in response to growth factors." (PMID 23866118, 2013). "Emerging evidences suggest that PI3K/Akt signaling mediates regulation and activation of HIF-1α in various human cancers." (PMID 23590596, 2013). "For correlation between HIF-1α and c-Met in other cancer tissues, only limited number of pancreatic tissue showed tendency of correlation with c-Met and HIF-1α expression." (PMID 23927384, 2013). "Recently, HIF1α has been revealed to play a central role in regulating the metabolic switch in cancer." (PMID 24216696, 2013). "In the context of increased oncogenic signaling, HIF1α expression is also increased in cancer cells by hypoxia-independent mechanisms that include increased transcription and/or translation of HIF1α mRNA, as well as, increased protein stability." (PMID 24216979, 2013). "Our results clearly uncover one of the crucial phenomenons of conversation between non cancer stem cells and cancer stem cells in hypoxia and show how HIF-1α and autophagy impact this process in Panc-1." (PMID 24305593, 2013). "Further investigation to clarify the antitumoral mechanisms revealed an inhibitory activity on angiogenesis and the release of related proangiogenic factors VEGF and HIF-1α, indicative of inhibitory activity related to cancer stem cell characters." (PMID 23533499, 2013). "The downstream target genes regulated by HIF-1α are involved in angiogenesis, hypoxic metabolism, cancer cell survival and invasion." (PMID 23496980, 2013). "On the other hand, another study reported that cancer invasion is accelerated by HIF-1α in a hypoxia-independent fashion." (PMID 24216696, 2013). "Our results also showed that baicalin and baicalein significantly inhibited expression of cancer promoting genes including HIF-1α, cMyc, NFkB, and VEGF." (PMID 23502466, 2013). "Although HIF1α is over expressed in a number of human cancers, the role of HIF1α in cancer progression is unclear." (PMID 23342109, 2013). "The effective chetomin dose range of 50-200 nM was very similar to that required for inhibition of HIF-1α action in other human cancer cell lines." (PMID 23866118, 2013). "Many studies have reported that the PI3K/Akt and MAP kinase pathways regulate VEGF and HIF-1α expression in cancer cells." (PMID 23936001, 2013). "Positive HIF-1α staining was observed in 47 out of the 152 patients (30.1%), and the staining was evident in the nuclei of the cancer cells." (PMID 23135628, 2013). "Through the sensing of oxygen level and/or the transcriptional activity of HIF-1α, hypoxia plays a key role in the reprograming of cancer cell metabolism." (PMID 24400010, 2013).
cancer (continued). "We have recently shown that GPER and CTGF are target genes of HIF-1α upon hypoxic conditions in cancer cells and cardiomyocytes." (PMID 23950890, 2013). "Previous work has revealed that cancer-promoting oncogenes and hypoxia-inducible factor (HIF-1α) induce a glycolytic shift." (PMID 23764021, 2013). "HIF-1α and its regulated markers including c-Met, CA9 and GLUT1 were reported to be highly expressed in various cancers and associated with poor prognosis." (PMID 23927384, 2013). "An HBS inhibitor targeting the P300– Hif1α protein interaction (often poorly regulated in cancer cells) was successful in disrupting the angiogensis pathway in cell based assays." (PMID 23717507, 2013). "Hypoxia inducible factor1α (HIF1α) affects a variety of malignant features, such as hypoxic cancer cell survival, via the regulation of a large number of genes, including carbonic anhydrase IX (CAIX)." (PMID 23372804, 2013). "3-(5′-hydroxymethyl-2′-furyl)-1-benzylindazole (YC-1), a novel anticancer drug initially developed as an inhibitor of HIF-1α, is currently undergoing preclinical trials against various forms of cancer." (PMID 23123638, 2013). "Previous studies have reported that HIF-1α is an important contributor involved in drug resistance against cancer chemotherapy." (PMID 24216696, 2013). "Based on our data, HIF-1α suppression should be considered as a potential mechanism contributing to the ability of HDACI to inhibit cancer cell growth." (PMID 24312289, 2013). "HIF-1α and c-Met have been known as contributing factors for cancer invasion and LN metastasis in various cancers." (PMID 23927384, 2013). "DER produces anti-cancer effects through several metabolic pathways, including inhibition of the IGF-1/PI3K/Akt/HIF-1α pathway which is used by cancer cells to promote proliferation and angiogenesis and inhibit apoptosis." (PMID 23755243, 2013). "This switch in metabolism from mitochondrial respiration to aerobic glycolysis is a common phenotype of cancer cells and is driven in part by the hypoxia-inducible factor 1α subunit (HIF-1α)." (PMID 26316984, 2013). "Our previous studies have demonstrated HIF-1α is regulated via PI3K/AKT signal pathway in cancer cells." (PMID 23762265, 2013). "HIF-1α which plays a key role in cancer progression by regulating a number of processes is the best characterized among the transcriptional regulators under hypoxia." (PMID 24305593, 2013). "Clinical studies have shown that HIF-1α overexpression correlates with advanced disease stages and poor prognosis among cancer patients." (PMID 24312289, 2013). "The hypoxia-inducible factor-1 alpha (HIF1A) plays a vital role in cancer initiation and progression." (PMID 23723982, 2013). "The difference in response of various HIF-1α target genes to changes in HIF-1α observed in different cancer cell lines remains to be investigated further." (PMID 23866118, 2013). "The authors found also that HIF-1α expression in cell nucleus represented an independent prognostic factor in women with such a cancer." (PMID 24153191, 2013). "Like Myc, HIF-1α also promotes glycolysis by inducing expression of glycolytic enzymes and when Myc expression is deregulated in cancers due to translocation or amplification, Myc, and HIF-1α cooperate to regulate glucose metabolism." (PMID 24350057, 2013). "CB-PIC at 40 μg/mL activated the phosphorylation of AMPKα and ERK in hypoxic SW620 cells and enhanced HIF1α accumulation up to 4 h in hypoxic SW620 cancer cells." (PMID 23589723, 2013). "Although HIF-1α expression was significantly higher in precancerous and cancer tissue than in normal tissue which was acquired around cancerous tissue, weak or moderate expression was observed in a large number of normal tissues." (PMID 23927384, 2013). "The increased hypoxia up-regulates HIF-1α expression and induces hypoxic selection of cancer cells and thus promotes their aggressiveness." (PMID 23651517, 2013).